SCN1A (sodium voltage-gated channel alpha subunit 1)
Diseases named in the same sentence as SCN1A in open-access papers (continued):
Sharing a sentence is not in itself a finding about the gene and the disease.
epilepsy (continued). "The current study has shown that rs2298771 of the SCN1A gene may be involved in the epilepsy susceptibility but not in the occurrence of drug-resistant epilepsy in the Pakistani population." (PMID 35136380, 2022). "Thus, we examined whether Trpv1 affects the epilepsy phenotype of the F1.Scn1a+/− mouse model of DS." (PMID 34079465, 2021). "In this study, meta-analysis was conducted to further explore the relationship between SCN1A and SCN2A gene polymorphisms and the efficacy of VPA in the treatment of childhood epilepsy, so as to provide etiological basis for individualized treatment of VPA in children with epilepsy." (PMID 34011048, 2021). "Thus, the dissociation between propensity to spreading depolarization on the one hand and epileptic seizures on the other hand could be a general feature beyond FHM3 and SCN1A-linked epilepsies." (PMID 34314446, 2021). "Such a situation could arise, for example, in the context of a patient with severe epilepsy found to harbor an SCN1A mutation not previously reported, with a phenotype not fully concordant with Dravet syndrome." (PMID 32783192, 2020). "Our results indicate that relatively common variants in epilepsy genes, which would not necessarily be classified as pathogenic, may play a large role in modulating SCN1A phenotypes." (PMID 32032478, 2020). "Importantly, the pathogenic SCN1A variants have a wide range of phenotypes, which may be also identified in patients with other types of DEE, such as EIEE or milder forms of epilepsy such as genetic epilepsy with febrile seizures plus (GEFS+)." (PMID 32899411, 2020). "Furthermore, identifying compounds that can differentially modulate different subtypes/isoforms of sodium channels may contribute to identifying new treatment strategies for SCN1A-related epilepsy." (PMID 28082152, 2018). "This will not be a simple task given the genetic complexity of epilepsy, in which mutations in different genes cause syndromes that are clinically indistinguishable, and mutations in a single gene, such as SCN1A, can cause a range of phenotypes varying from febrile seizures to severe EEs." (PMID 26302787, 2015). "Qualitatively, the peptide overlap occurs in human proteins canonically associated with epilepsy such as gamma-aminobutyric acid receptor subunit alpha-1 (GBRA1), gamma-aminobutyric acid type B receptor subunit 1 (GABR1), sodium channel protein subunits (SCN1A, SCN2A." (PMID 24982805, 2014). "In addition, encephalopathy is not a pure consequence of epilepsy but SCN1A mutation seems to play an additional, direct role." (PMID 24225340, 2013). "Our data support the hypothesis, that the SCN1A gene is not implicated in the pathogenesis of common forms of migraine, even when the phenotype is restricted by the presence of comorbidity with epilepsy." (PMID 21713554, 2011). "Nine shared genetic loci and six pleiotropic genes, including SCN1A, PGBD1, ZKSCAN3, ZKSCAN4, VRK2, and ZSCAN23, have been identified between epilepsy and psychiatric disorders." (PMID 41733899, 2026). "Notably, variants in the SCN1A, SCN8A, and SCN9A genes, which encode sodium channel proteins, were found with high frequency in both groups, suggesting that disturbances in sodium channel function may play a significant role in the pathophysiology of epilepsy." (PMID 40565516, 2025). "Mutations in four evolutionary and functionally similar α subunit genes, SCN1A, SCN2A, SCN3A, and SCN8A, lead to neurological diseases, including various types of epilepsy." (PMID 41007641, 2025). "In this single-center cohort of 139 pediatric patients with genetically confirmed SCN1A-, SCN2A-, SCN3A-, and SCN8A-related epilepsies, structural brain MRI abnormalities were identified in 37.4% of the patients." (PMID 41573391, 2025). "This study is one of the largest single-center comparative neuroimaging analyses of SCN1A-, SCN2A-, SCN3A-, and SCN8A-related epilepsies." (PMID 41573391, 2025).
epilepsy (continued). "The genetic underpinnings of epilepsy have helped in the classification of these syndromes, and examples now include rare monogenic forms involving KCNA2, KCNT1, and SCN1A." (PMID 40871704, 2025). "Many genetic polymorphisms play a role in the pathogenesis and treatment of epilepsy, e.g., SCN1A ABCG2, SCN1A, CYP3A5, and SCN2A." (PMID 39920787, 2025). "To address this gap, we analyzed structural brain MRI findings in a large single-center pediatric cohort with genetically confirmed SCN1A-, SCN2A-, SCN3A-, and SCN8A-related epilepsy." (PMID 41573391, 2025). "Of these, 114, 17, 1, and 7 patients had SCN1A-, SCN2A-, SCN3A-, and SCN8A-related epilepsy, respectively." (PMID 41573391, 2025). "Abnormalities were most frequent in the SCN2A (70.6%) group, followed by the SCN8A (42.9%) and SCN1A (31.6%) groups; one patient with SCN3A-related epilepsy also exhibited abnormal findings." (PMID 41573391, 2025). "Our results suggest that the pathogenic variant in SCN1A may lead to PD features without epilepsy." (PMID 39568674, 2024). "Three genes remained significant when we combined all epilepsy subtypes: DEPDC5 (log[OR]=2.1, P=3.4×10−15), NEXMIF (log[OR]=4.1, P=6.3×10−9), and SCN1A (log[OR]=2.7, P=3.5×10−8)." (PMID 36865150, 2024). "This study adds experimental evidence to previous reports of biallelic inheritance of SCN1A variants and suggests that some SCN1A variants do not cause epilepsy in the heterozygous state, but their recessive inheritance may cause it through the mild loss of Nav1.1 function." (PMID 39200163, 2024). "In the wide spectrum of the hundreds of epileptogenic genes, SCN1A and 2A are the most relevant, but also SCN3A and 8A have been found to be correlated with forms of epilepsy." (PMID 37240836, 2023). "During the very beginning of genetic epilepsy, with the studies of large families, SCN1A, SCN1B, and GABRG2 were identified as genes for monogenic epilepsies." (PMID 40217359, 2023). "In 8 patients, one or more epilepsy genes, GRIN2A, TET3, SCN1A, SCN8A, ADGRV1, DLG4, and SLC12A5, were found, and 12 patients had no genetic mutations." (PMID 38813507, 2023). "Although these three genes show mutations in a wide spectrum of neurological diseases such as epilepsy, autism spectrum disorder (ASD), and intellectual disability, two of those, SCN1A and SCN2A, are major ones." (PMID 37219072, 2023). "However, we went a step further in our study; we analyzed not only SCN1A but all known genes related to epilepsy, showing that neurological symptoms in children qualified as AEFI may be related to the occurrence of pathogenic variants in genes engaged in the development of the nervous system." (PMID 36674629, 2023). "The rs13405797 of SCN1A and rs2119067 of SCN3A were related to family history of epilepsy (p = 0.035 and 0.023)." (PMID 35801810, 2022). "Eighty-one epilepsy-related genes were detected; the gene most frequently detected was KCNQ2 (nine times), followed by PRRT2 (seven times), SCN1A (six times), SCN2A (five times), SPTAN1 (four times), and TSC2 (four times)." (PMID 35571021, 2022). "For example, although a SCN1A splicevariant with faster recovery from inactivation has been lost during evolution, probably toprotect from a gain of function effect, in the case of a pathological hyperactivitycondition such as epilepsy, its reintroduction in interneurons may be therapeutic." (PMID 36187146, 2022). "However, this variant has never been described in association with an SCN1A seizure disorder." (PMID 36229510, 2022). "Several epilepsy modifier genes, including CACNA1G and GABRA2, were first identified in the Scn1a+/− mouse model of Dravet syndrome and later confirmed as epilepsy risk genes in humans." (PMID 34086081, 2021).
epilepsy (continued). "For example, protein truncating variants in SCN1A are more likely than missense variants to cause Dravet syndrome rather than milder epilepsies, and the electrophysiological consequences of particular SCN2A variants might predict age of onset and treatment response." (PMID 34031551, 2021). "In our study, we found the relationship between the SNPs screened from SCN1A, SCN2A and UGT2B7, respectively, and VPA responses in Chinese Han people with epilepsy." (PMID 32185219, 2020). "Mosaicism in the proband has been reported in other genes such as PCDH19 (8.3%, 6/73), SCN1A (1.3%, 4/320), SCN2A (6.4%, 7/110), and CDKL5 (8.8%, 8/91), according to a recent large‐scale study of epilepsy‐related neurodevelopmental disorders." (PMID 30891744, 2019). "We find current evidence for this preferential enrichment among six epilepsy genes: CDKL5 (P = 1.1 × 10−12), KCNQ2 (P = 1.1 × 10−23), PCDH19 (P = 0.003), SCN1A (P = 9.7 × 10−9), SCN2A (P = 1.9 × 10−4), and SCN8A (P = 3.5 × 10−4)." (PMID 28864458, 2017). "The SCN1A gene (MIM#182389), coding for the voltage-gated Na+ channel alpha subunit NaV1.1, is the most clinically relevant epilepsy gene." (PMID 26990884, 2016). "In an earlier study on the same population we reported that a synonymous variant in GABRG2 rs211037 and SCN1A rs3812718 may have a putative role in increasing the risk of epilepsy, which was independent of its phenotype, that is, MTLE-HS or Juvenile myoclonic epilepsy." (PMID 24586633, 2014). "Now, only 2 genes, SCN1A and SCN3A remain in the list both of which are excellent candidates for an epilepsy phenotype." (PMID 19057649, 2008). "Even in SCN1A-related epilepsy, historically considered radiologically normal, follow-up imaging revealed a notable proportion with atrophy or hippocampal changes." (PMID 41573391, 2025). "As in many genetic disorders, the genotype-phenotype correlation in SCN1A-related epilepsy is often not straightforward." (PMID 41515912, 2025). "Drug-resistant epilepsy with frequent seizures was common in both SCN1A and non-SCN1A cohorts, with most individuals experiencing at least monthly seizures, whilst only 6.2% across the entire cohort were seizure-free at last follow-up." (PMID 39882024, 2025). "This may enter therapy practice, resulting allowing cyst PRISPR scientists to silence hyperexcitable circuits that are targeted by genetic drivers (e.g., SCN1A, SCN8A) related to seizures in the context of epilepsy." (PMID 40806492, 2025). "Some genes have been identified as modifiers of SCN1A-related seizure before, but all of these were epilepsy-related genes; no MYH9-modified seizure has been reported before." (PMID 39202364, 2024). "The association of SCN1A mutation, childhood SCZ and autism spectrum disorder without epilepsy was first reported in Psychiatry Research63." (PMID 39019913, 2024). "This cohort study aims to describe the evolution of disease features and health-related quality of life per life stage in Dravet syndrome and other SCN1A-related non-Dravet seizure disorders which will enable treating physicians to provide tailored care." (PMID 39239151, 2024). "This can be partially attributed to the high extent of SCN1A-related epilepsy not manifesting as DEE in our cohort." (PMID 38250573, 2023). "A strain-dependent phenotype is observed for Scn1a+/- mice with 129.Scn1a+/- mice having no overt phenotype and F1.Scn1a+/- mice exhibiting a severe epilepsy phenotype." (PMID 36701411, 2023). "Scn1a+/- mice on a congenic 129S6/SvEvTac strain (129.Scn1a+/-) are seizure-resistant, with no overt epilepsy phenotype." (PMID 36701411, 2023). "There are very few extant reports on epilepsy caused by SCN9A mutations, and the pathogenesis of GEFS+ without an SCN1A mutation remains arcane." (PMID 38174099, 2023).
epilepsy (continued). "Our results implicate KCNT1 as a therapeutic target for treatment of SCN1A and SCN8A epilepsy." (PMID 37901435, 2023). "Developmental and epileptic encephalopathies (DEE/EEs) are characterized by early onset of seizures, therapy resistance, neurodevelopmental delay, for example, as seen in channelopathies (e.g., GRIN2A-, SCN2A-, SCN1A-, and SCN8A-related epilepsies) or in metabolic conditions (e.g., SLC2A1)." (PMID 38125836, 2023). "Previous reports found that NaV1.1 expression is more predominant in the PV+ interneurons of the neocortex, hippocampus, and cerebellum, supporting the involvement of PV+ GABAergic neurons in SCN1A-related epilepsy." (PMID 38203200, 2023). "We also did not enroll SCN1A-related epilepsy cases in the OXC group, considering the exacerbation of epileptic seizures due to the loss of function of Nav1.1 (sodium voltage-gated channel alpha subunit 1) in most cases with pathogenic variants." (PMID 35720076, 2022). "In this study, we demonstrate a profound hyperexcitability of the corticohippocampal circuit in young adult Scn1a+/- mice that is not present at epilepsy onset using two-photon calcium imaging and cellular and synaptic physiology in an acute slice preparation." (PMID 35212623, 2022). "For example, rAAV-CRISPRa-mediated Scn1a activation at 4 weeks of age did not fully rescue epilepsy in mouse models of Dravet syndrome." (PMID 36410433, 2022). "Our study investigated the pH levels of saliva and urine in patients with SCN1A-related epilepsy, blood pH was not involved in the study." (PMID 36237607, 2022). "Other patients with drug-resistant focal epilepsy and mutations in SCN1A, CNTNAP2, STBXP1 genes were not seizure-free after epilepsy surgery regardless of lesional status (including HS, focal cortical dysplasia, encephalomalacia present on MRI)." (PMID 35492509, 2022). "In Dravet Syndrome (DRVT) (OMIM #607208), a severe form of drug-resistant epilepsy, the loss of function mutations of the SCN1A gene affect Nav1.1 and lead to a lack of neuronal inhibition in GABAergic interneurons resulting in neuronal hyperactivity." (PMID 35743236, 2022). "Sudden unexpected death in epilepsy (SUDEP) is known to occur, possibly because of lethal cardiac arrhythmias following severe seizures in Scn1a knock-in R1407X DS mouse model and Scn1a+/− knock-out DS mouse model." (PMID 33658306, 2021). "These precision diagnoses support the development of personalized therapies by providing insights into genotype‒phenotype relationships; for example, we would not use SCBs in SCN1A‐related epilepsy (Brunklaus, Ellis, Reavey, Forbes, & Zuberi, 2012)." (PMID 32400968, 2020). "However, potassium voltage-gated channel subfamily Q member 2 (KCNQ2), SCN1A, and GABRG2 are three established genes among top ten genes for common epilepsies." (PMID 33096746, 2020). "Though GS967 has been shown to be an efficacious antiepileptic in rodent models of SCN1A, SCN2A, and SCN8A epilepsies, the safety, tolerability, and antiepileptic efficacy of GS967/Prax330 in human patients with refractory epilepsy remains to be fully investigated." (PMID 32244818, 2020). "SCN9A is unlike the epilepsy-related VGSC-α subunit molecules SCN1A, SCN2A, SCN3A and SCN8A each of which is expressed primarily in brain, whereas SCN9A is expressed primarily in peripheral nerves." (PMID 33216760, 2020). "Nevertheless, a clearly defined phenotype-genotype correlation in SCN1A-related epilepsies other than Dravet or GEFS+ are non-existent, most likely due to a lack of data." (PMID 32581296, 2020).
epilepsy (continued). "The analysis identified polymorphic sequence variants as risk factors for the combined cohorts (focal and GGE) in SCN1A—perhaps the most well—known epilepsy gene—and in protocadherin 7 (PCHD7), a gene not yet known to be associated with epilepsy." (PMID 26302787, 2015). "One well-characterized epilepsy gene, SCN1A (sodium channel, voltage-gated, type I, alpha subunit), has previously been reported in both generalized and partial epilepsies, which gives some precedence for susceptibility genes occurring in different subtypes of epilepsy." (PMID 25875328, 2015). "It is possible that SCN1A alteration per se plays a role in psychomotor delay, affecting structures/pathways not involved in epilepsy." (PMID 24225340, 2013). "The mother reported no personal or family history of SCN1A‐related seizure disorders." (PMID 41317105, 2025). "Neuronal sodium channel genes, SCN1A, SCN2A and SCN8A, have been extensively involved in the pathophysiology of a broad spectrum of neurological disorders, including developmental and epileptic encephalopathy (DEE) in which epilepsy and neurodevelopmental comorbidities coexist." (PMID 41515912, 2025). "Epilepsy duration had no impact on regulation of SCN1A, SCN1A-dsAS, and SCN1A-usAS." (PMID 38283997, 2024). "On the 129S6/SvEvTac strain, Scn1a+/− mice did not develop epilepsy and lived a normal lifespan." (PMID 38862622, 2024). "In addition, targeting Kcnt1 transcript in Scn8a mutant mice doubled their lifespan and extended the survival of Scn1a mutant mice, suggesting KCNT1 could be a therapeutic target for the treatment of SCN1A and SCN8A epilepsy." (PMID 39513870, 2024). "As epilepsy duration also reflects the total load of seizures until surgery, the findings may suggest that seizure activity does not affect SCN1A, SCN1A-dsAS, and SCN1A-usAS expression in brain tissues derived from non-Dravet patients." (PMID 38283997, 2024). "There was no study on the saliva and urine pH in patients with SCN1A-related epilepsy." (PMID 36237607, 2022). "Besides SCN1A, PCDH19 is among the most relevant genes in epilepsy." (PMID 35111125, 2021). "In mouse models of epilepsy, SB2193 provided acute protection against 6 Hz-induced seizures but did not affect spontaneous seizures in Scn1a+/− mice." (PMID 37082241, 2023).